KAT6A (lysine acetyltransferase 6A)
Diseases named in the same sentence as KAT6A in open-access papers (continued):
Sharing a sentence is not in itself a finding about the gene and the disease.
colorectal cancer (4 papers, 2020 to 2024). A primary or metastatic malignant neoplasm that affects the colon or rectum. "The crucial role of TRIM24 in colorectal cancer cell proliferation is facilitated by the DANCR/KAT6A complex, which enhances TRIM24 association with H3K23ac and subsequently recruits YAP to chromatin, contributing to increased cell proliferation." (PMID 39160596, 2024). "Another research provided evidence that TRIM24 interaction with H3K23ac, mediated by the DANCR/KAT6A complex, enhances oncogenic processes associated with the YAP signaling pathway in colorectal cancer." (PMID 39160596, 2024). "A previous study revealed that DANCR interacts with KAT6A, which promotes proliferation of colorectal cancer cells." (PMID 32677374, 2020). "DANCR and KAT6A, long non‐coding RNA (lncRNA) molecules, have been reported to form a complex which mediates cell proliferation in colorectal cancer." (PMID 32677374, 2020). "We further found that the DANCR/KAT6A complex promoted the association of TRIM24 with H3K23ac, thereby inducing TRIM24‐mediated recruitment of YAP to the chromatin, and promoting proliferation of colorectal cancer cells." (PMID 32677374, 2020). "Our data also suggest that DANCR/KAT6A promotes the association between TRIM24 and H3K23ac, thereby enhancing the TRIM24‐mediated recruitment of YAP to the chromatin, resulting in the proliferation of colorectal cancer cells." (PMID 32677374, 2020). "For example, KAT6A showed a relatively higher mutation frequency in pancreatic and gastric cancers, and the majority of the mutations were missense mutations, whereas CREBBP showed the highest mutation frequency than other genes in gastric and colorectal cancers." (PMID 35422864, 2022). "We elucidated a previously unknown molecular mechanism involving DANCR/KAT6A‐mediated association of TRIM24 with H3K23ac, which subsequently results in enhancement of the oncogenic processes associated with the YAP signaling pathway in colorectal cancer." (PMID 32677374, 2020). "Thus, the DANCR/KAT6A complex upregulates TRIM24 in colorectal cancer." (PMID 32677374, 2020). "We found that the DANCR/KAT6A complex upregulated TRIM24, and promoted cell proliferation in colorectal cancer." (PMID 32677374, 2020). "TRIM24 is initially activated by the DANCR/KAT6A complex, thereby binding with H3K23ac and subsequently inducing TRIM24‐mediated recruitment of YAP to the chromatin, which ultimately promotes the proliferation of colorectal cancer cells." (PMID 32677374, 2020). "To gain insights into the precise role of the DANCR/KAT6A complex in mediating the function of TRIM24 in colorectal carcinoma, we inhibited the expression of DANCR or KAT6A in both SW620 and HT29 cells, and found that both mRNA and protein expression of YAP were inhibited." (PMID 32677374, 2020). "TRIM24 was shown to be oncogenic in colorectal cancer, but the relationship between the DANCR/KAT6A complex and TRIM24 in colorectal cancer had not previously been investigated." (PMID 32677374, 2020).
intellectual disability syndrome (3 papers, 2017 to 2023). "Both mutations were shown to be involved in mental retardation and intellectual disability syndrome by causing a truncation within the acidic domain of the KAT6A protein." (PMID 28789634, 2017).
ovarian carcinoma (3 papers, 2021 to 2024). A malignant neoplasm originating from the surface ovarian epithelium. "Our study showed that KAT6A is overexpressed in ovarian cancer and associated with prognosis." (PMID 33995658, 2021). "The expression of KAT6A was higher in PARPi‐resistant ovarian tumors compared to primary ovarian cancer." (PMID 38973255, 2024). "The interaction between KAT6A and PARP1 was increased in PARPi‐resistant ovarian cancer cells, as observed above; therefore, we further analyzed the relationship between KAT6A LLPS and the binding of the two proteins." (PMID 38973255, 2024). "We observed that deletion of KAT6A in PARP‐resistant ovarian cancer cells restored their sensitivity to PARPi." (PMID 38973255, 2024). "In this study, we explored the relationship between KAT6A and PARPi resistance in ovarian cancer cells." (PMID 38973255, 2024). "We conjectured that ovarian cancer cells with high KAT6A levels survive PARPi treatment and become the dominant clone, resulting in PARPi resistance, which was validated by in vitro experiments." (PMID 38973255, 2024). "Immunofluorescence assays revealed that KAT6A formed more biomolecular condensates in PARPi‐resistant ovarian cancer than in parental cells." (PMID 38973255, 2024). "In this study, we found that KAT6A levels were higher in patients with PARPi‐resistant ovarian cancer than in those with primary ovarian cancer." (PMID 38973255, 2024). "Overall, this evidence indicates that targeting the LLPS of KAT6A represses the development of PARPi‐resistant ovarian cancer cells." (PMID 38973255, 2024). "Taken together, KAT6A LLPS was enhanced in PARPi‐resistant ovarian cancer cells, and strengthens the interaction between KAT6A and PARP1." (PMID 38973255, 2024). "Overall, these data indicate that APEX1 is essential for the LLPS of KAT6A and the interaction of KAT6A with PARP1 in PARPi‐resistant ovarian cancer cells." (PMID 38973255, 2024). "In conclusion, the findings demonstrate the role of KAT6A LLPS in fostering PARPi resistance and suggest that repressing KAT6A LLPS can be a potential therapeutic strategy for PARPi‐resistant ovarian cancer." (PMID 38973255, 2024). "To confirm that KAT6A promotes the proliferation, migration and invasion in ovarian cancer cells, we knocked out KAT6A using CRISPR/Cas9 system in SKOV3 cells." (PMID 33995658, 2021). "To further support these findings, we examined KAT6A expression in ovarian cancer tissues and cell lines." (PMID 33995658, 2021). "Downregulation of KAT6A markedly inhibited the proliferation and migration abilities of ovarian cancer cells in vivo and in vitro." (PMID 33995658, 2021). "Collectively, these results demonstrate the oncogenic role of KAT6A in ovarian cancer by promoting cell proliferation and metastasis." (PMID 33995658, 2021). "Next, to further study the role of KAT6A in the metastasis of ovarian cancer in vivo, KAT6A-silenced cells were injected into the abdominal cavity to develop a peritoneal metastasis model." (PMID 33995658, 2021). "To study the potential role of KAT6A in ovarian cancer, we first analyzed its copy number alterations in The Cancer Genome Atlas (TCGA)." (PMID 33995658, 2021). "Pharmacologic inhibition of KAT6A using WM-1119 markedly enhanced the antitumor activity of cisplatin when applied to orthotopic ovarian cancer xenograft models." (PMID 33995658, 2021). "The results suggested that KAT6A exhibited higher expression in ovarian cancer cell lines than in normal ovarian cell lines and Hela cells." (PMID 33995658, 2021). "We then mutated K294 of COP1 to arginine (K294R, acetylation-dead mutant), which significantly impaired KAT6A-induced acetylation of COP1 in ovarian cancer cells." (PMID 33995658, 2021). "Here, our data identify that COP1 is a new KAT6A substrate, which advanced our knowledge of the function of KAT6A and COP1 and their association with ovarian cancer." (PMID 33995658, 2021).
ovarian carcinoma (continued). "The biological functions of KAT6A in ovarian cancer were evaluated by cell proliferation, wound healing and transwell invasion assays in vitro." (PMID 33995658, 2021). "Together, these data suggest that inhibition of KAT6A enhances cell apoptosis in ovarian cancer cells and sensitivity of ovarian cancer cell to platinum-based chemotherapeutics by decreasing β-catenin." (PMID 33995658, 2021). "We performed wound healing and transwell invasion assays and found that silencing KAT6A reduced the invasive ability in ovarian cancer cells." (PMID 33995658, 2021). "Genetic or pharmacologic inhibition of KAT6A enhanced ovarian cancer cell response to cisplatin, suggesting that KAT6A inhibition can sensitize ovarian cancer cells to platinum-based chemotherapeutics." (PMID 33995658, 2021). "Amplified genomic KAT6A was present in approximately 6% of ovarian cancer samples, which was higher than that of other ordinary acetyltransferases." (PMID 33995658, 2021). "To further investigate the biological function of KAT6A in ovarian cancer, we knocked down KAT6A with two different KAT6A shRNAs in SKOV3 and A2780 cells and a non-target shRNA was used as a control." (PMID 33995658, 2021). "KAT6A was significantly upregulated in ovarian cancer and correlated with poor survival in ovarian cancer patients." (PMID 33995658, 2021). "To characterize the mechanism by which KAT6A promotes ovarian cancer, we performed mass spectrometry (MS) to identify KAT6A-binding partners and proteins acetylated by KAT6A." (PMID 33995658, 2021). "Furthermore, KAT6A is a transcription coactivator that acetylates histones.[7c] To determine the mechanism by which KAT6A knockout impairs DDR in PARPi‐resistant ovarian cancer cells, we quantified the expression of key factors involved in DDR." (PMID 38973255, 2024). "Annexin V staining was used to detect apoptotic cells during the generation of PARPi‐resistant ovarian cancer cells, and the KAT6A level in non‐apoptotic (DTP) cells was much higher than that in apoptotic cells, indicating that ovarian cancer cells with high KAT6A levels survived PARPi treatment." (PMID 38973255, 2024). "Moreover, the interaction between APEX1 and KAT6A or PARP1 was enhanced in PARPi‐resistant ovarian cancer cells during olaparib + cisplatin treatment, indicating the formation of a more stable complex containing KAT6A, PARP1, and APEX1." (PMID 38973255, 2024). "Targeting KAT6A LLPS can be a potential therapeutic strategy for PARPi‐resistant ovarian cancer." (PMID 38973255, 2024). "In summary, our work provides new insights into the posttranslational modification of COP1 and β-catenin in ovarian cancer and highlights that KAT6A functions as an acetyltransferase of nonhistone proteins, by which KAT6A is implicated in tumor progression." (PMID 33995658, 2021). "To assess whether KAT6A promotes tumorigenesis of ovarian cancer through COP1-β-catenin pathway, we performed colony formation assay and transwell invasion assay." (PMID 33995658, 2021). "However, the re-expression of KAT6A neutralized the influence of KAT6A inhibition on apoptosis in ovarian cancer cells, indicating that KAT6A promotes ovarian cancer cell resistance to cisplatin treatment." (PMID 33995658, 2021). "Taken together, these findings demonstrated that KAT6A is upregulated in ovarian cancer, and the overexpression of KAT6A may predict poor survival in ovarian cancer patients." (PMID 33995658, 2021). "In this study, our data indicate that KAT6A is upregulated in ovarian cancer cells and tissues." (PMID 33995658, 2021). "Therefore, the mechanism by which KAT6A dysregulation contributes to tumorigenesis in some solid tumors, such as ovarian cancer, needs to be elucidated." (PMID 33995658, 2021).
ovarian carcinoma (continued). "Moreover, KAT6A, acting as a regulator of β-catenin, promotes the proliferation, invasion and metastasis of ovarian cancer cells and endows them with resistance to platinum-based chemotherapeutics by acetylating constitutive photomorphogenic 1 (COP1)." (PMID 33995658, 2021). "Our data demonstrate that KAT6A is critical for ovarian cancer." (PMID 33995658, 2021). "Additionally, the inhibition of KAT6A induced apoptosis and enhanced the sensitivity of ovarian cancer cells to cisplatin." (PMID 33995658, 2021). "Therefore, we examined the influence of KAT6A LLPS on PARPi resistance in ovarian cancer." (PMID 38973255, 2024). "Moreover, KAT6A was highly expressed in 30 of 40 (75%) ovarian cancer tissues." (PMID 33995658, 2021). "Additionally, based on previous research and our findings, we suspected that KAT6A may also exhibit oncogenic function in ovarian cancer." (PMID 33995658, 2021). "Taken together, these results demonstrate that the acetylation of COP1 by KAT6A stabilizes β-catenin by impairing β-catenin ubiquitination, resulting in the abnormal activation of the β-catenin signaling pathway and promoting the proliferation and metastasis of ovarian cancer cells." (PMID 33995658, 2021). "Next, we hypothesized that KAT6A may play a role in the metastasis of ovarian cancer." (PMID 33995658, 2021). "Both KAT6A LLPS and the interaction between KAT6A and PARP1 were enhanced in the PARPi‐resistant ovarian cancer cells." (PMID 38973255, 2024). "We previously discovered that lysine acetyltransferase 6A (KAT6A, also known as MYST3 or MOZ) is overexpressed in ovarian cancer." (PMID 38973255, 2024). "KAT6A‐ΔIDR, whose LLPS is impaired, significantly improved sensitivity to PARPi in ovarian cancer cells." (PMID 38973255, 2024). "KAT6A‐ΔIDR also induced resistance to cisplatin treatment by acetylating COP1 and stabilizing β‐catenin, similar to KAT6A‐WT in ovarian cancer cells." (PMID 38973255, 2024). "Further analysis identified an interaction between KAT6A and PARP1 in ovarian cancer cells, and this interaction between KAT6A and PARP1 was confirmed in HEK293T cells." (PMID 38973255, 2024). "Collectively, these findings suggest that KAT6A sequesters PARP1 away from DNA break sites, impairing PARP1 trapping during PARPi treatment of PARPi‐resistant ovarian cancer cells." (PMID 38973255, 2024). "However, the specific functions of KAT6A in ovarian cancer remain unclear." (PMID 33995658, 2021). "Therefore, KAT6A inhibition may be a potential therapeutic strategy in ovarian cancer treatment." (PMID 33995658, 2021). "Moreover, targeting KAT6A LLPS restored PARPi sensitivity, suggesting a promising clinical treatment strategy for PARPi‐resistant ovarian cancer." (PMID 38973255, 2024). "Notably, our analysis of these clinical samples revealed more interactions between KAT6A and PARP1 in PARPi‐resistant ovarian tumors than in primary ovarian cancer, suggesting a potential role of KAT6A in PARPi resistance." (PMID 38973255, 2024). "Here, it is shown that high levels of KAT6A promote PARPi resistance in ovarian cancer, regardless of its catalytic activity." (PMID 38973255, 2024). "In summary, KAT6A LLPS promotes PARPi resistance in ovarian cancer independent of its catalytic activity." (PMID 38973255, 2024). "Additionally, the interaction between KAT6A and PARP1 was enhanced in PARPi‐resistant ovarian cancer cells treated with olaparib and cisplatin in vitro." (PMID 38973255, 2024). "Conversely, KAT6A‐ΔIDR did not exhibit a significant difference in its ability to bind chromatin in either PARPi‐resistant or PARPi‐sensitive ovarian cancer cells." (PMID 38973255, 2024). "Here, KAT6A LLPS also enhanced the subsequent DDR capacity by impairing PARP1 trapping and reducing PARP1‐DNA complexes, which attenuated the cytotoxic effects of PARP1 trapping, leading to resistance to PARP inhibitors in ovarian cancer cells." (PMID 38973255, 2024).
ovarian carcinoma (continued). "Collectively, these findings indicate that KAT6A promotes PARPi resistance in ovarian cancer cells independent of its catalytic function." (PMID 38973255, 2024). "To determine whether KAT6A regulates the sensitivity of ovarian cancer cells to platinum-based chemotherapeutics, we measured the IC50 values of cisplatin in KAT6A-silenced cells and control cells." (PMID 33995658, 2021). "However, both KAT6AIDR‐FUS, whose LLPS was rescued by IDR from FUS, and KAT6AC543G/G657E enhanced PARPi resistance in ovarian cancer cells, indicating that KAT6A LLPS, but not its catalytic function, counteracted the effects of PARPi." (PMID 38973255, 2024). "Given that KAT6A LLPS reduces its capacity to bind chromatin, and deletion of the IDR domain from KAT6A disrupts the interaction between KAT6A and PARP1 in PARPi‐resistant ovarian cancer cells, our next inquiry focused on whether KAT6A impedes PARP1 trapping via LLPS." (PMID 38973255, 2024). "The IC50 values of cisplatin were 2.586 μM and 4.557 μM in KAT6A-silenced SKOV3 and A2780 cells, respectively, compared with 4.390 μM and 8.550 μM in the respective control cells, suggesting that KAT6A knockdown increased the sensitivity of ovarian cancer cells to platinum-based chemotherapeutics." (PMID 33995658, 2021). "Therefore, we concluded that KAT6A could promote activation of the Wnt/β-catenin pathway by acetylating COP1 and further promote tumorigenesis, cancer invasion and chemoresistance in ovarian cancer." (PMID 33995658, 2021). "Taken together, these results indicate that APEX1 impairs PARP1 trapping by enhancing KAT6A LLPS, and that the interaction between KAT6A and PARP1 is independent of its transcriptional regulatory function in ovarian cancer." (PMID 38973255, 2024). "Moreover, in a xenograft ovarian tumor model treated with olaparib and cisplatin, KAT6A knockout, but not WM1119 treatment, impaired PARPi resistance in ovarian cancer." (PMID 38973255, 2024). "Furthermore, we found that KAT6A knockout, but not catalytic inhibition of KAT6A using a small‐molecule inhibitor (WM1119), restored the PARPi sensitivity of ovarian cancer cells." (PMID 38973255, 2024). "In addition, inhibition of KAT6A LLPS, rather than its catalytic activity, impairs DNA damage repair and restores PARPi sensitivity in ovarian cancer both in vivo and in vitro." (PMID 38973255, 2024).
triple-negative breast carcinoma (3 papers, 2023 to 2025). An invasive breast carcinoma which is negative for expression of estrogen receptor (ER), progesterone receptor (PR), and human epidermal growth factor receptor 2 (HER2). "For example, in triple-negative breast cancer, KAT6A promotes interactions between SMAD3 and TRIM24 by mediating SMAD3 acetylation and inhibiting interactions between SMAD3 and TRIM33, thereby promoting tumor progression by regulating the immune microenvironment." (PMID 36611207, 2023).
Failure to thrive (2 papers, 2020 to 2024). Failure to thrive (FTT) refers to a child whose physical growth is substantially below the norm. "All five patients presented with feeding difficulties or failure to thrive, and patients 2, 4, and 5 also presented with neonatal hypotonia, traits reported in more than 70% of the KAT6A patients." (PMID 32041641, 2020).
Kabuki syndrome (2 papers, 2022). Kabuki syndrome (KS) is a multiple congenital anomaly syndrome characterized by typical facial features, skeletal anomalies, mild to moderate intellectual disability and postnatal growth deficiency. "This was relevant to three cases with Kabuki syndrome caused by KMT2D gene mutation, one case with KAT6A gene mutation, and one case with a 5.05-Mb draft genome sequence at chr10:130378377–135427935 q26.2–q26.3." (PMID 35612621, 2022). "Included were three cases with Kabuki syndrome caused by the KMT2D gene, one case with the KAT6A gene, and one case with a 5.05-Mb draft genome sequence at chr10:130378377–135427935 q26.2–q26.3." (PMID 35612621, 2022). "Overall, our results suggest sleep dysfunction is common among those with WSS, in line with recent cross-syndrome investigations involving rare genetic disorders including Smith-Magenis, Fragile X, Angelman, Prader-Willi, Cornelia de Lange, CHARGE, Williams, KAT6A, and Kabuki syndromes." (PMID 36313433, 2022).
lung carcinoma (2 papers, 2022 to 2024). "We treated lung cancer cells with WM-1119, a specific KAT6A/B inhibitor, and examined whether KAT6A/B inhibition induces lamin A/C downregulation." (PMID 36009484, 2022).
periodontitis (2 papers, 2024 to 2026). An acute or chronic inflammatory process that affects the tissues that surround and support the teeth. "Additionally, silencing FAM30A may alleviate the progression of periodontitis by regulating the miR-28-5p/KAT6A axis, reducing inflammation, and promoting bone formation." (PMID 41820893, 2026).